MMP9 (matrix metallopeptidase 9)
Diseases named in the same sentence as MMP9 in open-access papers (continued):
Sharing a sentence is not in itself a finding about the gene and the disease.
cancer (continued). "We also demonstrated that, unlike in untreated endothelial cells, the stimulation of these cells with the CV extract increased the production of IL-6, IL-8, and MMP-9, whereas cancer cells only released slightly more IL-6." (PMID 33260615, 2020). "Several studies have revealed that MMP-2 and MMP-9 are correlated with poor prognosis in cancer patients because they are related to interaction of integrins for adhesion and invasion of cancer cells." (PMID 32349276, 2020). "These two processes are particularly important when considering cancer development and have been associated to MMP activity, mainly MMP-9." (PMID 33308217, 2020). "Preventing CD147 glycosylation can lead to a lower expression of MMP2 and MMP9, which is essential in tissue remodeling and cancer metastasis." (PMID 33374805, 2020). "Functional blockade with monoclonal antibodies binding to α2, β1, and α2β1 integrin inhibited disaggregation and activation of MMP2/MMP9 in cancer spheroids." (PMID 33026975, 2020). "Low concentration of WFA (>95% viability) inhibits MMP-9 activity of cervical Caski and liver SK-Hep-1 cancer cells by downregulating Akt phosphorylation." (PMID 32429564, 2020). "An invasive GBM phenotype is characterized by high ability of cancer cells to degrade and migrate through the ECM, which is associated with the activity of matrix metalloproteinases MMP-2 and MMP-9, responsible for the ECM remodeling." (PMID 32545852, 2020). "MMP2 and MMP9 play an important role in cancer metastasis by promoting the degradation of extracellular matrix." (PMID 32226772, 2020). "SAA can stimulate the expression of MMP-9 by macrophages, which in turn facilitates cancer cell metastasis." (PMID 31907639, 2020). "To further our mechanistic knowledge of the pro-invasive role of STAT5a, we assessed the levels of pro-MMP-9, a pro-enzyme that facilitates degradation and proteolysis of the extracellular matrix to promote cancer cell dissemination and metastasis." (PMID 32633727, 2020). "In conclusion, this study suggests that pKAL exhibit anti-cancer effects on RT-R-MDA-MB-231 cells by suppressing CD44 and Oct 3/4, β-catenin and MMP-9, which appeared to be linked to RT resistance of RT-R-MDA-MB-231 cells." (PMID 32326231, 2020). "Further, the treatment with BEZ235 down-regulated the expression of MMP-9/-2 to suppress the cancer cell migration and invasion." (PMID 32466169, 2020). "IHC results indicated that the expression of the proliferation marker Ki67 and that of MMP9, which is involved in cancer invasion and metastasis, was significantly increased in the ARHGEF16-overexpressing xenograft tumors." (PMID 32811808, 2020). "A previous study has suggested that integrin-linked kinase overexpression downregulates MMP-9 during TGF-β2-induced EndMT, and elevated MMP-9 increases the invasive capacity of cancer cells." (PMID 32296578, 2020). "To elucidate the potential mechanism of this anti-migratory activity, we evaluated the effect of rHct-S3 on the expression level of the matrix metalloproteinases (MMP)-2 and MMP-9, playing a pivotal role in cancer cell invasion and metastasis." (PMID 33348592, 2020). "MMP-2 and MMP-9 expression is known to promote the migration/invasion and metastasis of cancer cells." (PMID 32922544, 2020). "Several inflammatory cytokines, such as CD31, BDNF, TFF3, Serpin E-1, VCAM-1, Vitamin D BP, and PDGF-AA, were significantly upregulated in cancer survivors while MMP9 and Osteopontin both had significant positive correlations with barriers to care." (PMID 32587352, 2020). "Gain-of-function mutations in RET lead to the development of specific human cancers and have been associated with the regulation of MMPs, including MMP2 and MMP9, which are thought to drive metastasis." (PMID 33020210, 2020).
cancer (continued). "Low METTL14 expression in cancer cells leads to high P2RX6 expression via the ATP-P2RX6-Ca2+-p-ERK1/2(Extracellular Regulated protein Kinases 1/2)-MMP9 (Matrix Metallopeptidase 9) signaling pathway, which promotes renal tumor cell metastasis and invasion." (PMID 32765970, 2020). "Studies have shown that MMP9 can not only degrade the extracellular matrix and basement membrane, and promote the invasion of cancer cells, but also play a key role in the process of epithelial‐mesenchymal transition to promote cell motility." (PMID 33377649, 2020). "According to previous studies, VEFG-1, ICAM-1, TGF-β2, MMP-1, and MMP-9 are key genes involved in the regulation of cancer cell metastasis and invasion." (PMID 32210104, 2020). "Elevated expression of CCR2 and MMP9 in ZEB1 wildtype F4/80low macrophages provided a positive feedback loop with ZEB1 wildtype cancer cells through cancer cell-expressed CCL2 cytokines." (PMID 32283687, 2020). "GMI inhibits tumor necrosis factor alpha (TNFα)-mediated matrix metallopeptidase 9 (MMP-9) expression and migration in A549 cancer cells." (PMID 33382817, 2020). "The levels of various proteinases, such as MMP-2 and MMP-9, are known to be increased during inflammatory diseases and in cancer." (PMID 32774424, 2020). "Bifidobacterium Aqueous Extracts Inhibit Cancer Cell Invasion by Regulating MMP-9 in NSCLC Cells Matrix metalloproteinase 9 (MMP-9) is known to play an important role in cancer cell invasion and metastasis." (PMID 32238777, 2020). "Inhibition of these transcription factors‐mediated signaling pathways suppresses MMP‐9 expression and cancer cell metastasis." (PMID 32180962, 2020). "TIMP-1 and TIMP-2 are capable of reducing the expression of MMP-2 and MMP-9 in suppressing metastasis and migration of cancer cells." (PMID 32992587, 2020). "Several studies have examined the roles of MMP9 in cancer development, progression, and its impact on patients’ survival and prognosis." (PMID 32445177, 2020). "Next, we used cBioPortal to evaluate the correlations between the levels of FGL2 and the cancer-promoting cytokines measured above (IL-10, MMP9, CCL5, TIM-3, IL-13, VCAM1, M-CSF and FGF-7) in ESCA tissues." (PMID 33323552, 2020). "MMP-2 and MMP-9 are well-known extracellular matrix (ECM)-degrading enzymes that have been reported to play crucial roles in cancer cell metastasis and invasion." (PMID 32225123, 2020). "E2F1 is implicated in regulating Zeb1 and Zeb2 expression, which promotes EMT, and MMP9, which drives cancer cell invasion." (PMID 32224870, 2020). "Although chemical inhibition of MMP-9 using broad-spectrum inhibitors seemed promising for cancer treatment, most of the inhibitors failed in the clinic due to adverse effects." (PMID 32575507, 2020). "On the other hand, the inhibition of JNK pathway repressed the c-Jun phosphorylation and NOX4 expression, followed by the inhibition of ROS production, MMP-1 and MMP-9 expression, and invasion ability in OA-treated cancer cells." (PMID 32641980, 2020). "A number of studies have shown that matrix metalloproteinases (MMP), especially MMP9, were often highly expressed in human cancers and correlated with the poor prognosis of patients." (PMID 32102440, 2020). "In conclusion, this study suggests pKAL exhibits anti-cancer effects on RT-R-MDA-MB-231 cells, by suppressing CD44 and Oct 3/4, β-catenin and MMP-9 which appeared to be linked to the RT resistance of RT-R-MDA-MB-231 cells." (PMID 32326231, 2020). "MMP-9 is a gelatinase that is highly expressed by cancer cells to degrade the ECM and facilitate their migration." (PMID 31983172, 2020). "In addition, MMP-9 and other neutrophil proteases associated with intravascular NETs may increase vascular permeability and degradation of the extracellular matrix, allowing extravasation of cancer cells and metastasis." (PMID 32244751, 2020).
cancer (continued). "MMP9 was barely detectable both in healthy colon mucosa and 10 cm and 20 cm away from the cancer: only few scattered cells through lamina propria, most likely macrophages, were MMP9 positive." (PMID 32286443, 2020). "MMP‐9 allows early stage/carcinoma in situ to progress into invasive disease and influences the later development of metastasis." (PMID 33021341, 2020). "Nrf2 overexpression promotes cancer progression and drug resistance in various cancers by activating several oncogenes such as matrix metallopeptidase 9, B-cell lymphoma 2, tumour necrosis factor α, and vascular endothelial growth factor A80–82." (PMID 33087811, 2020). "In particular, MMP-9 activity has been related to cancer pathology including invasion, angiogenesis, and metastasis." (PMID 32591509, 2020). "Consistently, AMD3100 has reduced MMP-9 production and hampered cancer metastasis in preclinical models." (PMID 32630531, 2020). "Later, exosomes released by normal cells residing in metastasis target organ(s) upregulate MMP-9 expression in the incoming cancer cells." (PMID 32630531, 2020). "TAMs in larynx carcinoma were also reported to secrete MMP9 to promote cancer growth and metastasis." (PMID 32283687, 2020). "Cancer cell invasion has been shown to be promoted by TNFα via MMP-9 expression, thus activating EMT." (PMID 32751717, 2020). "For instance, MMP-9 and MMP-2 upregulation is reportedly associated with cancer cell migration in various cancers." (PMID 32397656, 2020). "Several MMPs such as MT1-MMP, MMP-2, and MMP-9 were found correlated to the stages of cancer cell invasion progression." (PMID 32224968, 2020). "Noticeably, many of the matrix-bound growth factors which are released into a soluble form by MMP-9 effectively promote cancer cell locomotion." (PMID 32630531, 2020). "The overexpressions of MMP-2 and MMP-9 are related to the undesirable prognosis of patients with cancer." (PMID 32380783, 2020). "The IL-6/JAK2/STAT3/MMP-9 pathway has been described in a variety of human cancers and plays an essential role in microvessel proliferation and BM degradation." (PMID 32047820, 2020). "The suppression of cancer cell metastasis thru the down‐regulation of EGFR‐activated MMP‐9 has been presented." (PMID 32180962, 2020). "MMP-2 and MMP-9 were overexpressed in many cancers, and this was correlated with increases in cancer cell invasion and numbers/levels of metastases in many types of cancer." (PMID 31772330, 2020). "Among the various MMPs described and involved in malignant cancer cells, our attention has focused on gelatinase MMP-9, considered as the “prognostic biomarkers” for different malignant tumors." (PMID 32492880, 2020). "AIRE stimulates the expression of the cancer-related proinflammatory genes MMP9, CXCL10, and CXCL11." (PMID 32012175, 2020). "These evidences confirmed that the role of MMP-9 in OSCC cells is consistent with that in series of cancers and relevant clinical researches." (PMID 32382550, 2020). "MMP-2 and MMP-9 belong to a family of MMPs known to be gelatinases that promote the degradation of type IV collagen in the basement membrane during cancer cell invasion and metastasis." (PMID 33251135, 2020). "In previous studies, MMP-9 has been reported to destroy collagen IV, the main ingredient of basement membranes, and participate in remodeling, angiogenesis, and cancer cell metastasis in some solid tumors." (PMID 32382550, 2020). "The increase in MMP-9 levels at secondary sites helps metastasis establishment and outgrowth by both mediating cancer cell infiltration of the foreign tissue and releasing protumorigenic factors from the ECM." (PMID 32630531, 2020). "This shows a stronger interaction of the extract with the MMP9 protease enzyme than either with the estrogen receptor or progesterone receptor which is commonly present in luminal A cancer type." (PMID 33066411, 2020).
cancer (continued). "Another study by Gu and colleagues demonstrated a potential link between cancer cell survival and αvβ6/MMP-9 signaling in colon cancer cells." (PMID 32046329, 2020). "As one of the most studied MMPs, MMP-9 is well-known for the key roles in invasion of cancer cells and metastasis of tumors." (PMID 32293515, 2020). "The spread of cancer cells implies the degradation of the extracellular matrix by a variety of enzymes, among which the matrix metalloproteinase (MMP)-9 is particularly effective." (PMID 32630531, 2020). "The same applies to pioglitazone: pioglitazone was demonstrated to lower MMP9 levels in e.g., murine peritoneal macrophages, in lung and breast cancer cells, as well as in serum of atherosclerotic rabbit model." (PMID 32204537, 2020). "MMP‐9 is known to be involved in cancer initiation, invasion, angiogenesis, and metastasis in a variety of cancer cell types." (PMID 32253832, 2020). "MMP9 is a member of matrix metalloproteinase family, promoting cancer invasion, metastasis and angiogenesis." (PMID 32733809, 2020). "MMP-2 and MMP-9 provide metastasis of cancer cells into distant organs via degrading matrix collagen and basement membrane." (PMID 32992587, 2020). "Gelatinases such as matrix metallopeptidase 2 (MMP2) and MMP9 play crucial roles in cancer cell migration, invasion, and metastasis." (PMID 32708426, 2020). "Overexpressed MMP‐2 and MMP‐9 in BC cells facilitate the degradation of type IV collagen, increasing the metastasis and invasion of cancer cells." (PMID 33133558, 2020). "The mRNA levels of VEGF, NFkB, MMP2, MMP9, CDKN2a-p16 and MTNR1a were considerably higher in the carcinomas from PNT rats." (PMID 32499868, 2020). "An increase in the expression of OPN and MMP-9 suggest that RUNX2 contributes to the metastatic property of cancer cells." (PMID 31331331, 2019). "MMP-2 and MMP-9 are highly-expressed in malignant tumors, and have been shown to be involved in degradation of the ECM, a crucial component of the basal membrane, which consequently leads to cancer metastasis." (PMID 31783709, 2019). "In keeping with a differential spatial genome organization in cancers above and below the treatment threshold, we previously found MMP9 to reposition in 20% of low Gleason score cancers compared to 82% of intermediate/high Gleason score cancers." (PMID 31681438, 2019). "In the recent past, NGAL has gained interest for its ability to accelerate ECM breakdown by interacting with MMP9 and has thus been investigated as a potential biomarker of chronic kidney disease, cancer, and cardiovascular diseases." (PMID 31737648, 2019). "Considering that KLF8 was highlighted to bind the promoter of MMP-9 to induce its expression and stimulate cancer invasion, thus we further examined the alterations of MMPs in the downstream of KLF8." (PMID 31827393, 2019). "Of these, MT1-MMP (membrane type-1 matrix metalloproteinase, MMP14) is a key protease that activates pro-MMPs such as MMP2 and MMP9 and is associated with ECM degradation and cell migration during cancer metastasis." (PMID 31223610, 2019). "In the case of GCTB, the resection after surgery was the only available option to get the samples in order to measure the MMP-9 mRNA expression in peripheral tissue, confirming the overexpression in this type of cancer." (PMID 31426440, 2019). "Zoledronic acid, a bisphosphonate currently used in metastatic breast cancer, eliminates MMP9-producing TAMs and prolongs cancer patient survival." (PMID 31737559, 2019). "The prognostic value of MMP-9 in different types of cancer has been clearly identified, also demonstrating that its expression promotion and its transformation to active MMP-9, is dependent on NO synthesis, performed by the NOS-2 enzyme." (PMID 31683688, 2019). "Many studies have reported that the activation of NF-κB stimulated the expression of MMP-9 in various cancer cells." (PMID 31572058, 2019).
cancer (continued). "MMP9 was identified as a key factor in monocyte‐mediated extravasation by breaking the vessel barrier, as confirmed by significantly reduced extravasation rates of cancer cells via inhibited MMP9 function in monocytes." (PMID 31179226, 2019). "Previous studies showed that EGR1 downregulates MMP2 and MMP9 by binding directly to their promoter in cancer cells." (PMID 30845713, 2019). "The results of several studies have shown that PDPN is involved in ECM remodeling, and that the process of ECM degradation predominantly involves MMP-2 and MMP-9 whose expression correlates with prognosis in some cancer types." (PMID 30654768, 2019). "We also found that combining the compounds markedly downregulated MMP-2, MMP-9, and E-cadherin expression, which correlated with reduced cancer cell migration and invasion." (PMID 30967777, 2019). "MMP9 inactivating chemokines produced by cancer cells inhibits the inflow of neutrophils to the place of inflammation and, consequently, the development of esophageal cancer." (PMID 30728854, 2019). "In particular, this result evidences that, at an early time, only compound 41 in combination with K858 is able to downregulate the MMP-9 expression thus probably reducing the invasiveness of cancer cells." (PMID 31683688, 2019). "badia and Arbutus unedo present a lectin-like inhibitory action on cancer cell migration and MMP-2 and MMP-9 activity in HT29 cancer cells, which is unique to this subspecies, and which can be potentially used as an anticancer-agent." (PMID 31234551, 2019). "Preventing hypoxic upregulation of MMP-9, used in cancer cell and MDSC migration, via zoledronic acid is also being studied as combination therapy in PDA." (PMID 30931508, 2019). "Neutrophils produce the matrix metalloproteinase-9 (MMP-9), while dendritic cells CB11b+ participate in directing of cancer cells toward distant sites in the organism." (PMID 31133019, 2019). "NF-κB involved in the regulation of inflammatory factors including interleukins and MMP-9, is activated in most cancers via Erk1/2 and IKKα/β." (PMID 31754081, 2019). "In gastic cancer cells HGF can induce MMP-9 through upregulation in lipocalin-2 and activation of NFκB39." (PMID 30631034, 2019). "Our findings are consistent with those of a report that suggested that LFG-500 extracted from flavonoid inhibits cancer cell intrusion by suppressing the PI3K/AKT/NFκB/MMP-9 signaling pathways." (PMID 31068208, 2019). "Because of the ECM degradation by tumors, MMPs, particularly MMP-2 and MMP-9, play an essential role in the angiogenesis and metastasis of cancer." (PMID 31637006, 2019). "Taken together, these results suggest that YKS alleviates cancer pain via suppressing MMP-9 expression in bone metastasis model in mice." (PMID 31239855, 2019). "In conclusion, our results demonstrate that LPE reduces the invasiveness of gastric MKN-28 and AGS cancer cells through the reduction of IL-6-induced MMP-9/2 up-regulation." (PMID 31817563, 2019). "MMP-2 and MMP-9 primarily control cancer cell motility, and down-regulation of these proteins was reported across studies to reduce cancer metastasis." (PMID 31011289, 2019). "Studies have revealed that, both MMP-2 and MMP-9 can degrade type IV collagen and are frequently elevated in human cancer." (PMID 31921634, 2019). "A relationship seems to exist between MBP-1 expression and the decrease in the activity levels of MMP-9 in cancer tissues and MMP-2 in sera." (PMID 31416219, 2019). "These MMPs (MMP2 and MMP9) are important components for degradation of the ECM during cancer metastasis." (PMID 31263239, 2019). "It depicts a clear reactive chain that MMP‐9 in cancer cell lines sufficiently activates TGF‐β/SMAD signalling." (PMID 31264317, 2019). "There are strong lines of evidence to support this claim, because increased expression of extracellular matrix-degrading proteases, such as MMP9, is a prerequisite for the invasive phenotype of cancer cells." (PMID 31690033, 2019).